KIFC1 (kinesin family member C1)
Description:
Minus end-directed microtubule-dependent motor required for bipolar spindle formation. May contribute to movement of early endocytic vesicles (By similarity). Regulates cilium formation and structure (By similarity).
Synonyms: HSET; KNSL2
Tractability: Small molecule: a structure with a bound ligand is known; a high-quality ligand is known. PROTAC: ubiquitination databases record sites on it; a small molecule that binds it is known.
Target class: Other cytosolic protein
Gene: Protein-coding gene on chromosome 6 (33,391,429 to 33,410,441, forward strand). Ensembl gene ENSG00000237649.
Subcellular location: Nucleus; Cytoplasm, cytoskeleton, microtubule organizing center, centrosome; Cytoplasm, cytoskeleton, spindle; Early endosome
Subcellular location (Human Protein Atlas): Centrosome; Basal body; Primary cilium
Pathways (Reactome):
Hemostasis: Kinesins
Vesicle-mediated transport: COPI-dependent Golgi-to-ER retrograde traffic
Gene Ontology:
Molecular function: ATP binding; microtubule motor activity; microtubule binding
Biological process: mitotic metaphase chromosome alignment; mitotic spindle assembly; mitotic sister chromatid segregation; microtubule-based movement; spermatogenesis
Cellular component: membrane; early endosome; kinesin complex; microtubule organizing center; mitotic spindle; nucleus; centrosome; spindle
Genetic constraint (gnomAD): Loss-of-function variants: 37 observed, 68.99 expected, observed/expected ratio (o/e) 0.54, 90% interval 0.41 to 0.71. The upper end of that interval is the gene's LOEUF score, 0.71, which puts it in group 2 of 6, group 1 being the genes least tolerant of losing a copy. Missense variants: 721 observed, 888.93 expected, observed/expected ratio (o/e) 0.81, 90% interval 0.76 to 0.86. Synonymous variants: 325 observed, 358.47 expected, observed/expected ratio (o/e) 0.91, 90% interval 0.83 to 0.99.
Homologues: Orthologues: chimpanzee KIFC1 (99% identical), macaque KIFC1 (98% identical), dog KIFC1 (86% identical), rabbit KIFC1 (86% identical), pig KIFC1 (85% identical), guinea pig KIFC1 (80% identical), mouse Kifc1 (79% identical), rat Kifc1 (78% identical), mouse Kifc5b (77% identical), zebrafish kifc1 (40% identical). Paralogues in human: KIFC3 (30% identical), KIF14 (23% identical), KIFC2 (23% identical), KIF13B (20% identical), KIF3A (20% identical), KIF13A (20% identical), KIF3B (19% identical), KIF1B (19% identical), KIF3C (19% identical), KIF17 (19% identical), KIF1A (19% identical), KIF1C (19% identical), and 29 more.
Diseases named in the same sentence as KIFC1 in open-access papers:
KIFC1 is named in the same sentence as 78 diseases in open-access papers, as found by Europe PMC text mining. Sharing a sentence is not in itself a finding about the gene and the disease. The quoted sentences say what the papers report.
breast carcinoma (39 papers, 2014 to 2025). "In conclusion, our work identifies OTUD6B as a breast cancer-associated deubiquitinase that stabilises KIFC1 during mitosis, to support pseudo-bipolar spindle formation and cell survival." (PMID 39789388, 2025). "Nuclear KIFC1 expression is associated with an advanced tumor grade as well as poorer OS and progression-free survival in breast cancer." (PMID 36139643, 2022). "In breast cancer, high nuclear KIFC1 levels at the time of diagnosis have been associated with shorter overall and progression-free survival." (PMID 34945833, 2021). "We show that this PCAB score developed in malignant and normal breast tissue identifies a large proportion of TNBC patients with centrosome amplification who have poor prognosis and associates with KIFC1 addiction in breast cancer cell models." (PMID 29535384, 2018). "In support of the external validity of our analysis, we observed an adverse outcome associated with increased expression of several genes associated with breast cancer mortality that have been confirmed previously in the literature (KIFC1,28FAM83D,29GRB7,30UBE2C,31 and CLDN432)." (PMID 34714340, 2021). "Of our two candidates, we prioritised OTUD6B for mechanistic investigation, as it is frequently altered in clinical breast cancer and correlates with KIFC1 protein levels (Fig. EV1)." (PMID 39789388, 2025). "Up-regulation of KIFC1 expression is well known for breast cancer, and the protein has been suggested as a chemotherapy target, while over-expression of HN1L is related to tumor invasion in breast cancer." (PMID 40724805, 2025). "OTUD6B is commonly overexpressed in breast cancer, correlating with KIFC1 protein expression and worse patient survival." (PMID 39789388, 2025). "We and others have demonstrated the role of C/EBPβ and KIFC1 in breast cancer cell invasion and migration." (PMID 40448099, 2025). "KIFC1 is overexpressed in multiple cancers that exhibit centrosome amplification, including ovarian and breast cancer, consistent with an increased requirement to mediate centrosome clustering." (PMID 39789388, 2025). "KIFC1’s significance in malignancy is highlighted by its identification as a dependency factor in breast cancers, with its phosphorylation triggered by DNA damage leading to centrosome clustering and drug resistance." (PMID 38493150, 2024). "In breast cancers, we found significant upregulation of KIFC1, AURKB, BIRC5, and CDCA8 in tumor samples of both the GEPIA and UALCAN datasets, compared to normal samples." (PMID 39335162, 2024). "In breast cancer datasets, we found significant upregulation of both centrosome clustering proteins KIFC1, AURKB, BIRC5, and CDCA8 and the oncogenes FOXM1, ATAD2, and E2F1 in tumor samples compared to normal samples." (PMID 39335162, 2024). "Results revealed that KIF11, AURKB, TPX2 and KIFC1 are essential genes whose depletion in both breast cancer cell lines impacts cell viability." (PMID 37835564, 2023). "We demonstrated that TACC3 expression strongly positively correlates with KIFC1 mRNA, which is also correlated well with the CC score in breast cancer patients with high CA20 expression in the METABRIC dataset." (PMID 36864125, 2023). "AZ82 binds specifically to KIFC1, and treatment leads to centrosome declustering in BT-549 breast cancer cells that exhibit amplified centrosomes." (PMID 35053604, 2022). "Elevated levels of KIFC1 have been shown to confer drug resistance in breast cancer as well as prostate cancer." (PMID 33760984, 2021). "Several studies have verified that KIFC1 expression is related with poor prognosis in multiple tumors, such as non-small cell lung cancer, renal cell carcinoma, and breast cancer, and it does happen primarily by affecting the proliferation of tumor cells." (PMID 35111813, 2021). "A recent study has shown that KIFC1 phosphorylation induces chromosomal instability in breast cancer." (PMID 34768355, 2021).
breast carcinoma (continued). "High KIFC1 levels have been reported in various cancer types such as breast cancer, hepatocellular carcinoma, and ovarian cancer." (PMID 33760984, 2021). "The survival of breast cancer patients with a high KIFC1 protein expression was significantly lower than in patients with low KIFC1 expression." (PMID 33397932, 2021). "An Rb loss-of-function signature was established in The Cancer Genome Atlas by identifying genes that correlate with E2F1 and E2F2 expression in breast cancer, and KIFC1 emerged as one of the top genes included in the signature." (PMID 34945833, 2021). "KIFC1 expression was also found to be higher in breast cancer cell lines compared to premalignant cells, such as the MCF10A series and HMECs." (PMID 34945833, 2021). "Another study reported that KIFC1 knockdown increased the sensitivity to cisplatin in breast cancer." (PMID 34768355, 2021). "In previous study, a total of 21 proteomic signatures regulated by HMGA1 in breast cancer were reported, and three of them (KIFC1, LRRC59, and TRIP13) were verified to promote breast cancer progression." (PMID 33648560, 2021). "In the tumor recurrence group, about 70% of the breast cancer patients showed a high expression of KIFC1 (IHC score ≥8)." (PMID 33397932, 2021). "A meta-analysis showed that high expression of KIFC1 can be used as a predictor for patients with non-small cell lung cancer, ovarian cancer, breast cancer, and LIHC." (PMID 35111813, 2021). "Elevated expression levels of kinesins KIF14, KIF4A, KIF20A, and KIF23, KIF2C, and KIFC1 have been reported in breast cancer cell lines, other kinesins KIF10, KIF18A, and KIF15 have been linked to prognostic indicators in breast cancer patients." (PMID 32346924, 2020). "Studies have demonstrated that KIFC1 is involved in the pathogenesis and development of a variety of neoplasms, including breast cancer, ovarian cancer, prostate cancer, non-small cell lung cancer and esophageal squamous cell carcinoma." (PMID 31340839, 2019). "A recent study reported that the expression of KIFC1 is upregulated in DTX-resistant breast cancer cell lines compared with that of DTX-sensitive cell lines." (PMID 30744126, 2019). "One initial driver for this study was the idea that identifying a DUB for KIFC1 might present an alternative way to therapeutically target centrosome clustering in breast cancer, particularly TNBC." (PMID 39789388, 2025). "We found that OTUD6B is frequently amplified or overexpressed leading to elevated protein levels in the TCGA breast cancer cohort, where it is associated with worse survival (Fig. EV1E) and basal-like TNBC (Fig. EV1G), and positively correlates with KIFC1 protein levels (Fig. EV1H)." (PMID 39789388, 2025). "Interestingly, KIFC1 still participates in cisplatin resistance in bladder cancer, docetaxel resistance in breast cancer and prostate cancer, and temozolomide (TMZ) resistance in glioblastoma." (PMID 38112634, 2023). "Recent studies have shown that KIFC1 is involved in cisplatin resistance in breast cancer." (PMID 34768355, 2021). "KIFC1 is overexpressed and confers a poorer prognosis across various cancer types such as hepatocellular carcinoma, non-small cell lung cancer, ovarian cancer, prostate cancer, and breast cancer." (PMID 34945833, 2021). "Besides, the overexpression of KIFC1 can inhibit docetaxel-mediated apoptosis in breast cancer cells and prostate cancer cells." (PMID 31895691, 2019). "When the PCAB score was calculated in breast cancer cell line (BCCL) pellet FFPE blocks from lines previously characterized for KIFC1 dependency this revealed a linear correlation between PCAB score and the NPI caused by KIFC1 knockdown." (PMID 29535384, 2018). "Given that AA women with breast cancer suffer a more aggressive disease course than White women, we hypothesized that KIFC1 would hold greater value as a prognostic biomarker in AA women with TNBC." (PMID 28218233, 2017).
breast carcinoma (continued). "Nuclear KIFC1 (nKIFC1) predicts worse outcomes in breast cancer, but its prognostic value within racially distinct triple-negative breast cancer (TNBC) patients is unknown." (PMID 28218233, 2017). "Moreover, the cancer type more enriched for KIFC1 overexpression was found to be breast cancer, followed by lung and prostate cancer." (PMID 26527623, 2016). "Thus, we were inquisitive to evaluate the expression of KIFC1, a well known clustering molecule, which is highly expressed in aggressive breast cancers, particularly the triple negatives." (PMID 25028599, 2014). "Herein, we analyzed KIFC1 RNA levels and their associations with clinical features and outcomes among AR-low and AR-high TNBC tumors in three distinct publicly available gene expression datasets and in the breast cancer gene expression database (bc-GenExMiner)." (PMID 38003261, 2023). "In addition, KIFC1 has been identified as a malignant cell dependency protein in breast cancers." (PMID 35053604, 2022). "Therefore, KIFC1 has emerged as a biomarker of aggressive breast cancer." (PMID 36139643, 2022). "In addition, the overexpression of KIFC1 suppresses DTX-mediated apoptosis in breast cancer cells." (PMID 30744126, 2019). "With the notable exception of MCF7, the percentage of cells with amplified centrosomes was higher in breast cancer than in normal mammary epithelium cell lines (Fig. EV1A) and correlated with both KIFC1 and OTUD6B levels (Fig. EV1B–D)." (PMID 39789388, 2025). "Studies showed that KIFC1 and KIF2A were both highly expressed in breast cancer and promoted the proliferation and migration of breast cancer cells." (PMID 38713252, 2024). "A recent study showed that KIFC1 phosphorylation by ATM and ATR kinase is involved in drug resistance in breast cancer." (PMID 34768355, 2021). "What is more, overexpression of KIFC1 increased the pools of free tubulin and promoted DTX resistance in breast cancer." (PMID 30744126, 2019). "Studies on breast cancer, prostate cancer and HCC have suggested that kinesin family proteins, including KIFC1, are responsible for drug resistance." (PMID 31340839, 2019). "KIFC1 expression was decreased in HMGA1-silenced breast cancer cells, while HMGA1 was decreased in KIFC1 knockdown HCC cells in our study." (PMID 31340839, 2019). "These genes include AURKB, BUB1, CHEK1, FOXM1, KIFC1, and TTK7, five of which, BUB1, CHEK1, FOXM1, KIFC1, and TTK, we have also identified and have functionally validated to have a selective requirement for cell growth in breast cancer cell models." (PMID 29535384, 2018). "We found that KIF23, KIF20A, KIF4A, KIFC1 and PRC1 were expressed at high levels in all investigated breast cancer cell lines." (PMID 28061449, 2017). "By interrogating a breast cancer gene expression data set (GOBO data set), we obtained the expression of KIFC1, LRRC59, and TRIP13 genes for tumor samples stratified according to HU and PAM50 subtypes, ER status, and histological grade." (PMID 26527623, 2016). "As already shown in breast cancer, we also find several members of the Kinesin protein family (KIF11, KIF15, KIF23, KIF2C and KIFC1) to be upregulated in patients with high expression of ATAD2." (PMID 26308378, 2015). "We therefore selected four patient-derived xenograft (PDX) models of breast cancer (BRPF212, BRPF280, BRPF232, and BRPF008) to analyze the changes in KIFC1 protein levels after treatment with conventional chemotherapeutic drugs including cisplatin and etoposide." (PMID 33397932, 2021). "Specifically, KIFC1 expression has been demonstrated to be higher in basal-like versus luminal breast cancers and higher in TNBCs versus non-TNBCs." (PMID 34945833, 2021). "The top differentially expressed genes (unadjusted P ≤ .001) were all upregulated and included KIFC1 (OMIM 603763), FAM83D (OMIM 618380), UBE2C (OMIM 605574), CLDN4 (OMIM 602909), GRB7 (OMIM 601522), and PKMYT1 (OMIM 602474), each of which have previously reported roles in breast cancer progression." (PMID 34714340, 2021).
breast carcinoma (continued). "Four independent siRNA oligos, validated to deplete KIFC1 mRNA and/or protein, induced a substantial reduction of cell viability over a 6-day period only in the cell models with centrosome amplification, regardless of breast cancer subtype." (PMID 29535384, 2018). "Due to the fact that the KIFC1 mRNA level is shown to be significantly diminished in various PJ34 treated breast cancer cell lines, we speculate that PJ34 might be transcriptionally suppressing the expression of KIFC1 given that PARP has been formerly reported to be a transcriptional regulator." (PMID 27102297, 2016).
prostate carcinoma (12 papers, 2016 to 2025). A carcinoma that arises from epithelial cells of the prostate gland. "KIFC1 is also associated with docetaxel resistance in breast cancer and prostate cancer." (PMID 35327439, 2022). "Previously, we showed that KIFC1 is associated with CD44 in prostate cancer and gastric cancer." (PMID 34768355, 2021). "The study investigating the effects of KIFC1 inhibitors in prostate cancer also highlighted the significance of KIFC1 in cancer." (PMID 38112634, 2023). "Recently KIFC1 has shown to play a role in the progression of many different cancers, however, the involvement of KIFC1 in the progression of prostate cancer (PCa) is still not well understood." (PMID 33760984, 2021). "Recently, KIFC1 has shown to be an important factor in prostate cancer progression and drug resistance by inhibiting cell death and conferring docetaxel resistance." (PMID 33760984, 2021). "Previously, we reported that KIFC1 is involved in cancer progression in prostate cancer (PCa)." (PMID 30744126, 2019). "Indeed, recent studies have shown that KIFC1 is highly expressed in prostate cancer, hepatocellular carcinoma, serous ovarian adenocarcinomas, non-small cell lung cancer, renal cell carcinoma, triple-negative breast cancer, and that it is associated with poor prognoses." (PMID 35327439, 2022). "Furthermore, relative to the non-castration-resistant prostate cancer cell line (LNCaP), the expression of KIF14, CENPE, KIF15, KIF18B, and KIFC1 was significantly elevated in the castration-resistant PCa cell line (DU145)." (PMID 40956849, 2025).
hepatocellular carcinoma (10 papers, 2019 to 2025). A malignant tumor that arises from hepatocytes. "Our previous experiments showed that KIFC1 is significantly overexpressed in hepatocellular carcinoma and contributes to the progression of the disease, resulting in a poor prognosis." (PMID 40857057, 2025). "Previous studies from our group demonstrated that KIFC1 overexpression in hepatocellular carcinoma promotes malignant behaviours via the PI3K/AKT pathway." (PMID 40857057, 2025). "For example, KIFC1 is highly expressed in hepatocellular carcinoma and promotes hepatocellular carcinoma cell proliferation and invasion." (PMID 40612867, 2025). "KIFC1 activation contributes to HCC development of hepatocellular carcinoma by modulating the transcriptional activity of HMGA1." (PMID 38457554, 2024). "Moreover, there have been reports suggesting the potential of KIFC1 as a biomarker for hepatocellular carcinoma." (PMID 38112634, 2023). "Once KIFC1 activated abnormally, it was able to promote the epithelial-mesenchymal transition (EMT), chemo-resistance, and proliferation of hepatoma cells, thereby facilitating HCC progression both in vitro and in vivo." (PMID 38433242, 2024). "The functions and underlying mechanisms of kinesin family member C1 (KIFC1), a member of the kinesin-14 family, in the pathogenesis of hepatocellular carcinoma (HCC) have not been fully elucidated." (PMID 31340839, 2019).
endometrial cancer (9 papers, 2023 to 2025). Primary or metastatic malignant neoplasm involving the endometrium (mucous membrane that lines the endometrial cavity). "As in the reported studies, KIFC1 is widely expressed in cancer cells, such as prostate, ovarian, breast, lung, and endometrial cancers, and we report here, pancreatic cancer." (PMID 40612867, 2025). "The results revealed significant upregulation of KIFC1 in most cancer types, particularly melanoma, cervical cancer, ovarian cancer, endometrial cancer, lung cancer, stomach cancer, colorectal cancer, head and neck cancer, and urothelial cancer." (PMID 38457554, 2024). "A recent investigation demonstrates that KIFC1 promotes aerobic glycolysis through the HMGA1/c-myc pathway, and the inhibition of KIFC1 promoted the inhibition of endometrial cancer cell growth." (PMID 36984785, 2023). "Furthermore, there is evidence that KIFC1 promotes endometrial cancer centrosome amplification by regulating ubiquitination of PLK." (PMID 40857057, 2025). "Interestingly, PLK4 activity was correlated to KIFC1, where KIFC1 overexpression promoted the expression of PLK4 and centrosome amplification in endometrial cancer HEC-1A cells, suggesting the importance of PLK4 in the progression of endometrial cancer." (PMID 41488365, 2025).